MMP2 (matrix metallopeptidase 2)
Diseases named in the same sentence as MMP2 in open-access papers (continued):
Sharing a sentence is not in itself a finding about the gene and the disease.
cancer (continued). "In addition, the expression of MMP2 in AKR1B1 knockdown cancer cells also decreased significantly compared with the control group." (PMID 34646828, 2021). "GRK6 decreases the expression of the cancer-promoting genes MMP2 and MMP7." (PMID 33920915, 2021). "In those cancer cells, LIF promoted invadopodia-associated characteristics and markers, such as tyrosine kinase substrate with five SH3 domains (TKS5), cortactin (CTTN), matrix metallopeptidase 2 (MMP2) and SRC proto-oncogene (SRC)." (PMID 34361105, 2021). "Therefore, the intratumor activity of both MMP-9 and MMP-2, that are involved in facilitating cancer cell dissemination at secondary sites, was investigated by zymography." (PMID 34764332, 2021). "However, certain MMPs, such as MMP-2, -9, and -13, can be overexpressed in pathological states, including cancer and metastasis." (PMID 33498946, 2021). "Moreover, the inclusion of CN in the g-dECM bioink allows the regulation of the size of cell aggregates, and the expression of MMP2, β-catenin, and integrin β1, by controlling the stiffness of the cancer microenvironment." (PMID 33816446, 2021). "Moreover, several studies have reported that EGCG offers potential protection from neurodegeneration or can be considered an inhibitor of cancer cell metastasis via the inhibition of the expression and activity of several proteins such as MMP-2 and MMP-9." (PMID 33498927, 2021). "With the exception of MMP-9 mRNA in OVCAR4 cells, CIS and PTX both significantly increased the expression of MMP-2, -9 and -14 mRNAs and concurrently increased the expression of three CSC markers (OCT4A, EpCAM, CD133), associated with chemoresistance in the cancer cell lines." (PMID 35047406, 2021). "Human studies indicate that ROCK2 promotes cancer growth, in addition to degrading MMP2." (PMID 34773987, 2021). "MMP-2/9 targeted ACPP was also constructed with a cyclic RGD peptide on the d-glutamic acid arm (e9) for additional targeting to the αvβ3 integrin that is found on the membranes of many cancer cells." (PMID 33801967, 2021). "Studies also showed the phlorotannins may also protect the cancer cell by the inhibition of ROS-generating MMP-2 and MMP-9 via the NF-κB pathway." (PMID 34336128, 2021). "Due to the discovery of a strong correlation between expression levels of NNMT and matrix metalloproteinase-2 (MMP-2), that is suggested to play an important role in cancer cell invasion, further analyses were carried out to disclose the interplay between both determinants of cellular invasiveness." (PMID 34439880, 2021). "VIM and MMP2 are also markers of CAFs, which promote cancer progression and metastasis." (PMID 33747932, 2021). "Additionally, in cancer tissue, the expression of MMP2 was also higher in cancer cells than in normal cells, which was consistent with the literature." (PMID 34976953, 2021). "ESCO2 histone acetyltransferase curbs MMP2 and also encourages apoptosis in cancer cells." (PMID 35096000, 2021). "MMP-7 may also contribute to cancer progression by the activation of MMP-2 and -9, and two epithelial–mesenchymal transformation pathways (RTK/RAS and the β-catenin)." (PMID 33946534, 2021). "In particular, MMP-2/-9 are key regulators of cancer invasion." (PMID 33833342, 2021). "MMP-2 and MMP-9 can degrade components of the ECM such as type IV collagen to release tension and allow growth and invasion of tumors and as such are implicated in the late stages of cancer." (PMID 33596971, 2021). "Moreover, cancer cells secrete ECM metalloproteinase inducer (EMMPRIN) that promotes the synthesis of matrix metalloproteinase (MMP)-2 by PSCs, which is crucial for degradation of the basement membrane and thereby influence cancer invasion and metastasis." (PMID 33546284, 2021). "OPRK1 knockdown could inhibited cell viability and migration in cancer cells, accompanied with the decreased proteins and genes expression of N-cadherin, Snail, MMP2 and Vimentin, while the E-cadherin expression was increased." (PMID 34461834, 2021).
cancer (continued). "MMP-2 and -9 are the most prominent MMPs modulating cancer cell invasion." (PMID 35145899, 2021). "The potential inhibition of migration and invasion by B. nigra extract was also evidenced by the downregulation of MMP2, MMP9 and Snail genes, and upregulation of E-cadherin gene (hallmark of cancer metastasis) in a concentration-dependent manner at the transcriptional and translational levels." (PMID 32365503, 2020). "Additionally, genistein down-regulates MMP-9 expression in A549 cell lines and MMP-2 expression in human prostate cancer, thereby preventing invasion and metastasis of cancer cells." (PMID 33113890, 2020). "Furthermore, MMP2/9 correlated with regulatory T cells (Tregs) across 30 cancer types (median Rs = 0.57)." (PMID 32988398, 2020). "Fucoidan-induced changes in the expression levels and activities of other MMP members in malignant cells are not fully understood, even though MMPs other than MMP-2 and -9 also play important roles in malignant aggressiveness and prognosis in various types of cancers, including BC." (PMID 33333858, 2020). "For example, MMP2/9 highly correlated with exhausted T cell marker PDCD1 across 23 cancer types." (PMID 32988398, 2020). "Moreover, the area under the ROC curve of M-CSF and the combined analysis of M-CSF with CA 125 and SCC-Ag were larger than the area of MMP-2 or TIMP-2 in all stages of cancer." (PMID 30820752, 2020). "MMP-2 (gelatinase A) and MMP-9 (gelatinase B) are both cancer associated." (PMID 32765634, 2020). "A qPCR analysis also revealed elevated expression of the cancer stemness-related genes MMP2, MMP9, Nanog and SOX2, suggesting that NPC43 PD_R cells may have acquired an increase in cancer stemness." (PMID 33243298, 2020). "However, in many cancer cell lines, the MMP-2 and MMP-9 expression at both transcriptional and translational levels was regulated by PI3-K/AKT signalling pathway." (PMID 33003361, 2020). "High expression of CLDN-1 was reported in intestinal type gastric cancer that correlated with lymph node metastasis, advanced TNM (classification of malignant tumors) stage, recruitment, and activation of MMP-2 and MMP-9, which are all responsible for enhanced cell invasion and metastasis." (PMID 31952355, 2020). "However, though there are many reports on the anticancer activities of A. vera, to our knowledge, there are no studies which correlate its anticancer activities with MMP-9 and MMP-2 enzymatic activity inhibition in cancer cells." (PMID 33308217, 2020). "CircPUM1 was found in cancer cell-derived exosomes and could be transferred to act on the peritoneum, regulating peritoneal expression of MMP2 and, thus, promoting tumor dissemination." (PMID 32943996, 2020). "Furthermore, YB-1 promotes cancer migration and invasion by activating the metalloproteinases MMP2 and MT1." (PMID 32842598, 2020). "None of the 5 tested polymorphisms showed a correlation with cancer risk in studied groups, although for MMP-2, MMP-7 and MT2A non-significant differences in genotypes frequencies among cases and controls were observed." (PMID 32765800, 2020). "In addition, acting as downstream targets of MAPKs, MMP2 and MMP9 were also highly induced when circ_0032821 was upregulated in GC cells, thus causing the cancer cell invasion." (PMID 32165864, 2020). "TIMP-1 reduces expression of MMP-2 in impairing cancer migration." (PMID 33187385, 2020). "Our observation of aspirin-treated mice harbouring cancer cells with increased MMP2 and MMP9 gene expression is intriguing and whether this has resulted from aspirin acting on the platelets or the cancer cells themselves is still to be determined." (PMID 32246008, 2020). "MMP-2 has been reported to play critical roles in cancer invasion and metastasis." (PMID 32429421, 2020). "We next tested whether non GBM cancer cells similarly responded to increased osmolality by producing more uPA, MMP-2 and MMP-9." (PMID 32060379, 2020).
cancer (continued). "In addition to gene regulation, CK2 also suppresses gelatinolytic activity by phosphorylating the matrix metalloproteinase-2 (MMP-2) to inhibit cancer cell invasion." (PMID 32823607, 2020). "Hypoxia stimulates the interaction of vIIIEGFR with the integrin β3 in GBM cells, activating a signalling pathways c-SRC-dependent resulting in the up-regulation of the cancer cell invasion markers, like matrix metalloproteinase-2 (MMP-2) and matrix metalloproteinase-9 (MMP-9)." (PMID 32486205, 2020). "We revealed for the first time that the actinoporin was able to inhibit cancer colony formation and cell migration via suppression of MMP-2 and MMP-9 expression and induce cell apoptosis via activation of caspase-3, cleavage of PARP, activation of Bax and suppression of Blc-2 expressions." (PMID 33348592, 2020). "In addition, zymography confirmed the stronger secretion of MMP2 activity exclusively in 3D-growing cancer cells, providing the evidence that the 3D environment enhances the expression of genes and proteins related to the ECM." (PMID 33585217, 2020). "We sought to further investigate whether Rac1 inactivation was responsible for inhibition of cancer cell invasion by suppressing NF-κB-mediated MMP-2/-9 expression, by transient ectopic expression of NF-κB p65 in cells in the presence of GA or NSC23766." (PMID 32823607, 2020). "LOXL2, E‐cadherin, and MMP2/9 are involved in cancer cell invasion and metastasis." (PMID 31162697, 2020). "Besides, the metastasis of cancer cells is also negatively affected by curcumin in promoting DOX efficacy via MMP-2 downregulation and TIMP-1 upregulation." (PMID 33187385, 2020). "In addition, expression of MMP-2 was dysregulated in sh1 and sh2, it was hence postulated to increase the breakdown of extracellular matrix proteins insomuch as to induce cancer cell metastasis." (PMID 33123284, 2020). "Thus, we suggest that surfactin has the anti-cancer effects by directly inhibiting MMP-2 and MMP-9 levels in response to PM." (PMID 32922544, 2020). "There are two key factors during the process of cancer invasion and metastasis: MMP-2 and TIMP-1." (PMID 32368309, 2020). "Finally, the positive control, the hydroxamate-based MMP inhibitor NNGH, showed IC50 values of 29–187 mM for antiproliferation activities against various cancer cell lines, and against MMP-2 and MMP-9 showed values of 0.0091 and 0.0088 mM, respectively." (PMID 32967141, 2020). "MMP-2 is a metalloproteinase that has a proven role in the pathogenesis of cancer." (PMID 32751899, 2020). "MMP-2 activity, as a proteolytic enzyme, is necessary for cancer invasion and metastasis." (PMID 32582823, 2020). "MMP-2 was reported to be a determinant of metastatic potential for cancer cell." (PMID 32143669, 2020). "MMP‐9 and MMP‐2 are two key family members of MMPs that are able to degrade the basement membranes and extracellular matrix, and thus facilitate invasion and metastasis of malignant tumour cells into other organs or tissues." (PMID 32237037, 2020). "In addition to CAFs, leader positions of collectively migrating units can be supplied by cancer cells that over-express MMP-2 whenever they are included in spheroids containing either FAK-proficient or FAK-deficient cells." (PMID 33321813, 2020). "In addition, MMP2/9 positively correlated with most inhibitory immune checkpoints across multiple cancer types." (PMID 32988398, 2020). "A number of other authors have also pointed to the role of MMP-2 in cancer invasion and metastasis." (PMID 30820752, 2020). "Interestingly, SETD3 regulates the expression of other genes associated with cancer such as β-actin, FOXM1, FBXW7, Fascin, eNOS, and MMP-2." (PMID 32042016, 2020). "Indeed, PTTG1 has been shown to transcriptionally activate expression of a wide range of target genes, including c-Myc, FGF-2, cyclin D3, p21, and MMP-2, most of which are critically involved in cancer proliferation and metastasis." (PMID 33250768, 2020).
cancer (continued). "In addition to the anti-proliferative activity via hTERT down-regulation, chrysin- and curcumin-loaded nanoparticles can suppress metastasis of cancer cells via reducing expressions of MMP-2 and MMP-9." (PMID 32992587, 2020). "Since the (a) site is commonly enriched with H3K27ac among cancers with high MMP2 expression, and it is about 10 kb upstream of the promoter region, we consider the (a) site to be the MMP2 enhancer." (PMID 32499570, 2020). "Thus, the microgravity environment up-regulated expression of MMP-2 and MMP-9, which cause cancer cell migration." (PMID 31601869, 2019). "LDD-1819 treatment reduced the expression of MMP-1 and MMP-2 in the cancer cells." (PMID 31489353, 2019). "In another study, proanthocyanin, γ-oryzanol, and γ-tocotrienol extracted from red rice fractions were found to have anti-invasion activity against HT1080 and MDA-MB-231 cancer cells by decreasing the expression and activity of matrix metalloproteinase-2 and -9 (MMP-2 and -9)." (PMID 31374888, 2019). "FN1 can induce abnormal expression of some MMPs, such as MMP9/MMP2 and promote proliferation, migration, and invasion in thyroid and gastric cancers." (PMID 30886783, 2019). "proMMP2/MMP2 activation pathway is critical for cancer cell metastasis." (PMID 31598171, 2019). "In our cancer pain model, the mice had a short life, and so they may have died before MMP-2 could increase, and bone destruction progresses more in approximately ten days, which is associated with not only neuropathic pain but also nociceptive pain." (PMID 31239855, 2019). "The present results showed that β-catenin and MMP-2 were highly expressed in cancer cells." (PMID 31119174, 2019). "MMP9 and MMP2 are common indicators of cancer migration and invasion." (PMID 31346317, 2019). "Interestingly, RNA-seq and IPAD data from miR-29-treated D283 cells suggest that p-JNK is downregulated as well, which is known to upregulate MMP-2 expression and promote cancer cell migration." (PMID 31382461, 2019). "RNF128 regulates the EGFR/MAPK/MMP-2 pathway to drive these aggressive cancer features in ESCC." (PMID 31216681, 2019). "Furthermore, pectolinarigenin markedly impaired cancer cell migration and invasion by down-regulating phosphorylated-Stat3, and expression of matrix metalloproteinase (MMP)-2, MMP-9, while up-regulating the expression of TIMP2." (PMID 31649548, 2019). "It is generally known that cancerous cells target and invade normal healthy cells and studies have confirmed that MMP-2 enables this process by playing a pivotal role in the progression of cancer to distal parts of the body from its point of origin through metastasis." (PMID 31857956, 2019). "Furthermore, blocking TGF-β signaling by silencing TGF-ΒR1 in HCC cells attenuates VE-cadherin/MMP-2/LAMC2 expression and inhibits cancer-associated fibroblast (CM-CAF)-promoted VM formation." (PMID 31772665, 2019). "Moreover, the same effect was observed in the expression of MMP-2, known to be critically involved in cancer cell invasion." (PMID 30621163, 2019). "Importantly, hypoxia is an important factor that induces cancer metastasis, following 7 weeks, hypoxia increased expression of MMP2 and ADAMTS1." (PMID 30755679, 2019). "Furthermore, a recent study has shown that the blocking activation of STAT3 can reduce the expression of MMP2 and inhibit the invasion ability of cancer cells." (PMID 31546234, 2019). "Here we report that hYSK1 directly interacted with p21WAF1/Cip1, thereby resulting in SP-1-mediated suppression of p16INK4a promoter activity and increased MMP-2 expression under hypoxic condition leading to increased proliferation and migration of cancer cells." (PMID 30646538, 2019). "A most recent study suggested that CEACAM1 overexpression significantly suppressed cancer cell proliferation, induced cancer cell apoptosis, and inhibited cancer cell invasion and migration possibly through activation of caspase-3 and downregulation of MMP-2 and MMP-947." (PMID 31358815, 2019).
cancer (continued). "In addition, mesenchymal markers, angiogenesis-related proteins, and cancer stem-like cell marker proteins and MMP-2/-9 mRNAs were upregulated in metastatic pulmonary tissues treated with IR." (PMID 30743214, 2019). "Overexpression of MMP2 or MMP9 has been reported in various types of cancer, including OSCC." (PMID 30871117, 2019). "Further, they upregulate MMP–2/9 in cancer cells, increasing their motility." (PMID 31248001, 2019). "Furthermore, the previously study also noted that MMP-2 rs243865 C>T and MMP-9 rs3918242 C>T gene polymorphisms were closely related to cancer susceptibility." (PMID 31192912, 2019). "Some phenolic acids detected in numerous grains could inhibit cancer cell metastasis by suppressing enzyme matrix metalloproteinase-2 (MMP-2) via Ras/Akt/NF-κB signaling pathway." (PMID 31174320, 2019). "In our previous study, we found that MMP-2/-9 play important roles in the invasion of cancer cells." (PMID 31632484, 2019). "The mesenchymal-like cancer cells in our model have the ability to express diffusible MMP-2." (PMID 30903592, 2019). "Notably, our study showed that MMP1 was targeted by adenine and oxymatrine, and previous evidence has indicated that oxymatrine inhibits the proliferation and facilitates apoptosis of cancer cells through downregulating MMP2 and MMP9 expression." (PMID 31275410, 2019). "Therefore, MMP2 was selected as a marker to indicate the possible role of OCT3 in the biological behavior of malignant tumors by detecting the impact of OCT3 expression on MMP2 expression." (PMID 31524264, 2019). "The MMP2 was expressed on a comparable level in cancer and NLNT (p = 0.372; Wilcoxon test)." (PMID 31921636, 2019). "In addition, the ethanol extract of “Snow lotus” showed anti-metastatic property by inhibiting invasion and motility of cancer cells via activation of an inhibitor for matrix metalloproteinase-2/-9 (MMP-2/-9)." (PMID 32009958, 2019). "Some studies have suggested that MMP-2 is involved in metastasis, while other studies have reported that collagen production by cancer cells might also contribute to motility." (PMID 29440967, 2018). "Among the matrix metalloproteinases (MMPs), a family of zinc endopeptidases with the role on extracellular matrix protein degradation leading to the metastasis of cancer cells, specifically, the serum activities of MMP-2 and MMP-9 correlate with the invasive potential of cancer." (PMID 30115027, 2018). "Collectively, MMP-2 has been considered as a target for cancer therapy." (PMID 29495404, 2018). "Therefore, the inhibition of MMP2 activation has been suggested to be a potent strategy for the prevention of cancer cell metastasis." (PMID 29573200, 2018). "A total of 43 genes reside within 10 kb of these regions (column B), including those involved in cancer pathways (e.g. MMP2), angiogenesis (e.g. VEGFA), hypoxia response (e.g. SCAP), and neural development (e.g. KCNQ2), with downregulation of these loci being the dominant transcriptional effect." (PMID 29587824, 2018). "Moreover, Real-time measurement of MMP2 expression to determine important metastatic biomarker of HeLa cells opened up a new paradigm to understand the possible dynamics of cancer cells to spread metastasis by traversing through microcapillaries in human body." (PMID 30478455, 2018). "Active MMP2 in turn promotes invasion by and metastasis of different cancers." (PMID 30174795, 2018). "Interestingly, analysis of the exosome content derived from cancer and stromal cells reveals the presence of membrane-bound and soluble MMPs, including MMP-2." (PMID 29874869, 2018). "Furthermore, CH-5 decreases the expression and activity of MMP-2 protein, which plays a critical role in cancer cell migration and invasion." (PMID 29385675, 2018). "However, all these methods suffer from limitations in the detection of dynamic MMP-2 activities and visualization of the distribution of MMP-2 activity in cancer cells and their microenvironment." (PMID 29466303, 2018).